VCAM1 (vascular cell adhesion molecule 1)
Diseases named in the same sentence as VCAM1 in open-access papers (continued):
Sharing a sentence is not in itself a finding about the gene and the disease.
osteosarcoma (continued). "The strategy to suppress the expression level of CXCL1 could effectively decrease the VCAM-1 expression, which has the beneficial response for inhibiting migration, invasion, and wound healing abilities in osteosarcoma." (PMID 34760697, 2021). "Moreover, IGFBP3 was also found to inhibit the osteosarcoma cell migration via attenuating the PI3K/AKT/VCAM-1 signaling." (PMID 34349117, 2021). "In consideration of the fact that HPAECs-secreted CXCL1 recruits osteosarcoma cells and contributes to lung metastasis, and our findings showing that VCAM-1 expression is positively correlated with CXCR2 in osteosarcoma tissue, we analyzed VCAM-1 expression after HPAECs CM treatment." (PMID 32079335, 2020). "Incubation of osteosarcoma cells with CXCL13 increased VCAM-1 expression." (PMID 32847038, 2020). "We found that HPAECs-induced secretion of CXCL1 promoted VCAM-1 expression in osteosarcoma cells, which suggests that VCAM-1 may assist with the transendothelial migration of cancer cells." (PMID 32079335, 2020). "Furthermore, the recruitment of osteosarcoma cells by HPAECs CM was inhibited by transfection with VCAM-1 shRNA." (PMID 32079335, 2020). "Interestingly, it was suggested, that CTGF stimulates osteosarcoma metastasis by upregulating VCAM-1 expression." (PMID 33087801, 2020). "Finally, the CXCR2 chemical inhibitor SB225002 and CXCR2 shRNA confirmed that the CXCL1/CXCR2 axis is required for VCAM-1 expression and mobility of osteosarcoma cells." (PMID 32079335, 2020). "Moreover, the inhibition of FAK and c-Src countered the decrease in miR-513c-5p synthesis induced by NGF, which suggests that NGF modulates VCAM-1-dependent monocyte adhesion to osteosarcoma cells by inhibiting miR-513c-5p levels via the FAK and c-Src pathways." (PMID 39247831, 2024). "The current study showed that the CXCL1 could signal the CXCR2/focal adhesion kinase (FAK)/phosphatidylinositol-3-kinase (PI3K)/Akt/nuclear factor-kappa B (NF-κB) pathway to increase VCAM-1 expression and subsequently upregulate the metastasis ability of human osteosarcoma cells." (PMID 34760697, 2021). "Therefore, the CXCL13/CXCR5 interaction regulates VCAM-1 synthesis and osteosarcoma cell migration." (PMID 32847038, 2020). "Thus, CXCR2 expression correlates with VCAM-1 expression and tumor progression in osteosarcoma." (PMID 32079335, 2020). "Thus, inhibiting VCAM-1 expression may be an effective strategy for treating osteosarcoma metastasis." (PMID 32847038, 2020). "Transfecting osteosarcoma cells with an miR-513c-5p mimic significantly reduced NGF-induced monocyte adhesion, VCAM-1, and CD206 expression." (PMID 39247831, 2024). "Six of these genes are increased (MYOM2, VEGFA, MUC1, IHH, GLI1 and GRIA1) and seven are decreased (VCAM1, EGFR, GPC3, IGF2, GNG12, GNGT1 and C3) in localized patients with poor prognosis that either relapse or die due to osteosarcoma." (PMID 38538763, 2024). "The fact that FAK inhibitors reversed NGF-enhanced c-Src phosphorylation suggests that in human osteosarcoma, NGF activates the FAK and c-Src signaling pathways and in so doing promotes VCAM-1-regulated monocyte adhesion." (PMID 39247831, 2024). "Upregulating the expression of the vascular cell adhesion molecule 1 (VCAM-1) stimulates human osteosarcoma cell migration and drives osteosarcoma lung metastasis." (PMID 37893141, 2023). "This activation of CXCR2 on a cancer cell in the blood is associated with an increase in vascular cell adhesion molecule-1 (VCAM-1) expression on cells with activated CXCR2, something that has been observed in the metastasis to the lung by osteosarcoma." (PMID 35216283, 2022). "We next examined levels of CXCL1 and VCAM-1 expression in osteosarcoma specimens, to determine the prognostic relevance of CXCL1 and VCAM-1 in osteosarcoma progression." (PMID 34760697, 2021).
osteosarcoma (continued). "Immunohistochemistry staining of clinical osteosarcoma specimens revealed positive correlations between CXCR2 expression and pathology stage and also vascular cell adhesion molecule 1 (VCAM-1) expression." (PMID 32079335, 2020). "We found that VCAM-1 expression increased with tumor stage and was positively correlated with CXCR2 expression in osteosarcoma specimens." (PMID 32079335, 2020). "When HPAECs-conditioned media was incubated in osteosarcoma cells, we observed that the CXCR2 receptor and FAK/PI3K/Akt/NF-κB signaling cascade were required for VCAM-1 expression." (PMID 32079335, 2020). "Transfection of cells with VCAM-1 siRNA reduced levels of VCAM-1 expression and CXCL13-induced promotion of osteosarcoma cell migration, indicating that CXCL13 facilitates VCAM-1-dependent osteosarcoma cell migration." (PMID 32847038, 2020). "Preincubation of HPAECs CM with CXCL1 neutralized antibody reversed VCAM-1 expression, demonstrating that HPAECs-secreted CXCL1 can directly stimulate VCAM-1 expression in osteosarcoma cells." (PMID 32079335, 2020). "In order to better quantify the contribution of SLAMF6 to cellular adhesion we created a line of U20s osteosarcoma human epithelial cells that stably over expressed SLAMF6 and VCAM-1." (PMID 31199820, 2019). "Cells with VCAM-1 shRNA transfection could suppress CXCL1-induced VCAM-1 protein expressions and migration in MG63 osteosarcoma cells." (PMID 34760697, 2021). "Incubation of all three osteosarcoma cell lines with PLCβ, PKCα, and c-Src inhibitors (U73122, GF109203X, and PP2, respectively) antagonized CXCL13-induced increases in cell migration and VCAM-1 production." (PMID 32847038, 2020).
dengue (20 papers, 2012 to 2025). "Perfusion indices were correlated negatively with VCAM-1 and Ang-2 levels, suggesting that endothelial activation may underlie the flow disturbances observed in dengue." (PMID 27230099, 2016). "There was an increase in the expression of other inflammatory mediators related to increased vascular permeability and cause of shock and deaths in dengue: RANTES, VEGF-R2, and VCAM-1." (PMID 39967674, 2025). "In relation to severe dengue, in addition to CRP and AST, SDC-1 and VCAM-1 were also significant associations." (PMID 37838744, 2023). "Several groups have reported endothelial cell activation with high levels of circulating ICAM-1 and VCAM-1 in dengue patients." (PMID 38235130, 2023). "We investigated the association of 10 biomarkers (VCAM-1, SDC-1, Ang-2, IL-8, IP-10, IL-1RA, sCD163, sTREM-1, ferritin, CRP) with the development of severe/moderate dengue (S/MD)." (PMID 34154705, 2021). "In addition, early increased levels of VCAM-1 and SDC-1 were also associated with increased risk of severe dengue, while increased IL-8 and lowered albumin were associated with an increased risk of DHF." (PMID 37838744, 2023). "Among patients with dengue, PPV and MFI were negatively correlated with molecules associated with endothelial activation, including VCAM-1 (partial correlations, −0.45 for PPV and −0.46 for MFI; both P < .001) and Ang-2 (partial correlations, −0.33 and −0.29, respectively; both P = .001)." (PMID 27230099, 2016). "VCAM-1 not only mediates adhesion of monocytes as well as lymphocytes but is also critical for endothelial cell survival and in the previous study have been shown to be increased in dengue patients compared to other febrile illnesses." (PMID 24647042, 2014). "In conclusion, higher levels of the ten biomarkers (VCAM-1, SDC-1, Ang-2, IL-8, IP-10, IL-1RA, sCD163, sTREM-1, ferritin, and CRP), when considered individually, are associated with increased risk of adverse clinical outcomes in both children and adults with dengue." (PMID 34154705, 2021). "This differs from other endothelial biomarkers such as angiopoietin-2 and VCAM-1 that tend to peak during the critical phase and suggests that hypoargininemia, high arginase, and reduced NO bioavailability are some of the earliest abnormalities in the pathophysiology of dengue." (PMID 28673038, 2017). "Other mediators and soluble factors such as monocyte chemoattractant protein 1 (MCP-1), soluble vascular cell adhesion molecule 1 (VCAM-1), and thrombomodulin were also found to be increased in severe dengue." (PMID 32751561, 2020). "A systematic review and meta-analysis identified key biomarkers predictive of severe dengue manifestations, including elevated levels of CRP, AST, IL-8, and decreased albumin levels for DHF, and increased levels of VCAM-1, syndecan-1, AST, and CRP for severe dengue (SD)." (PMID 40100920, 2025). "Non-dengue tissues exhibited little or none expression of RANTES, VEGFR-2 and VCAM-1, however, TNF-α was detected in cells around the centrilobular vein." (PMID 37457689, 2023).
endometriosis (20 papers, 2013 to 2025). The growth of functional endometrial tissue in anatomic sites outside the uterine body. "The expression of VCAM-1 on peritoneal mesothelial cells was also found to be associated with endometriosis, which creates the “soil” for an endometriotic seed." (PMID 29772648, 2018). "VCAM-1 levels have been shown to be increased in the serum of women with endometriosis, which may be used as a potential diagnostic biomarker for endometriosis." (PMID 31443713, 2019). "Lower VCAM-1 levels have been reported in women with endometriosis that may be associated with UI." (PMID 40650261, 2025). "Our data showed that the function of the protein as a regulator of cell invasion of epithelial endometriosis cells might differ from those in stroma, while downregulation of VCAM-1 following LINC01133 knockdown was associated with an increase of cellular invasion." (PMID 34445100, 2021). "And mRNA levels of VCAM-1 were higher in normal peritoneal tissue samples from women with endometriosis compared to control normal peritoneal tissue samples." (PMID 41188339, 2025). "This picture is consistent with our findings, specifically the overexpression of ICAM1 and VCAM1, particularly in deep infiltrating endometriosis tissue and in peritoneal lesions (PeL) or eutopic endometrium (PE) of ES patients." (PMID 40747097, 2025). "The levels of angiogenin, CD105, ICAM-1, CXCL10, leptin, lipocalin-2, MMP-9, osteopontin, RBP4, PAI-1, ABP, CD31, TIM-2, and VCAM-1 were higher in the endometriosis group than in the control group." (PMID 34072419, 2021). "VCAM-1 is an important downstream effector of the NF-κB signaling pathway, contributing to the progression of endometriosis." (PMID 34266426, 2021). "The loss of VCAM-1 was shown to attenuate the TGF-β1 induced proliferation, migration and invasion of endometriosis stroma cells derived from ovarian endometriomas." (PMID 34445100, 2021). "In this study, we aimed to investigate the functional role of vascular cell adhesion molecule 1 (VCAM-1) in TGF-β1-mediated endometriosis in vitro." (PMID 31443713, 2019). "The expression of cell adhesion molecules such as ICAM-1 and VCAM-1 plays a vital role in the development of endometriosis, especially in the early stages of pathogenesis." (PMID 31636643, 2019). "Our findings suggest that the TGF-β1/Smad/VCAM-1 pathway is a vital inducer of the occurrence and development of endometriosis." (PMID 31443713, 2019). "Vascular cell adhesion molecule 1 (VCAM-1) has been reported to be aberrantly expressed in patients with endometriosis." (PMID 31443713, 2019). "Women with severe (grade 3 and 4) endometriosis have been shown to have higher blood levels of sVCAM-1 compared to control patients, while other authors have measured increased peritoneal VCAM-1 mRNA in endometriosis patients." (PMID 29772648, 2018). "Women with endometriosis had increased peritoneal mRNA expression of VCAM-1 during menstrual compared with luteal phase." (PMID 23843796, 2013). "The novelty of this study was the finding of the combination of VCAM-1, VEGF, sICAM-3, angiopoietin-1, and sTie-2 protein changes, which have not been reported in UI at any time but rather individually in endometriosis, a condition that has been associated with UI." (PMID 40650261, 2025). "Estrogen levels can be higher in endometriosis and were positively correlated with VCAM-1 and negatively with Tie-2 levels, but more research needs to be undertaken to understand the significance of these findings that suggest these proteins are involved in the reproductive axis." (PMID 40650261, 2025). "Higher levels of VCAM1 are found in ectopic endometriotic lesions and in the eutopic endometrium of individuals with endometriosis and may contribute to disease establishment and progression." (PMID 38402336, 2024). "Finally, compared with controls, C3 and VCAM1 were highly expressed in endometriosis tissue samples." (PMID 36660246, 2023).
endometriosis (continued). "ICAM-1 alone or together with soluble vascular cell adhesion molecule 1 (VCAM-1) may be a promising biomarker for diagnosing endometriosis." (PMID 35935991, 2022). "Our results revealed that knockdown of VCAM-1 impedes TGF-β1-mediated proliferation, migration, and invasion of endometriotic cyst stromal cells, suggesting that VCAM-1 may serve as a promising therapeutic target for endometriosis." (PMID 31443713, 2019). "Our findings suggest that VCAM-1 may be a novel and effective therapeutic target for the treatment of endometriosis and offer scientific evidence for its clinical application." (PMID 31443713, 2019). "Finally, C3 and VCAM1 were highly expressed in endometriosis tissue samples compared with controls and may be potential biomarkers of endometriosis, which are helpful for the early diagnosis of endometriosis." (PMID 36660246, 2023). "The expression profiles of key endoplasmic reticulum stress-related genes, including EPAS1, F8, VCAM1, and VWF, exhibited significant disparities between endometriosis specimens and both adjacent normal endometrial tissues and control endometrial tissues." (PMID 41188339, 2025). "Compared with the control group, high C3, VCAM1, ITGB2, and C3AR1 expression had statistical significance in endometriosis among the hub DEIRGs." (PMID 36660246, 2023). "Vascular cell adhesion molecule-1 (VCAM-1), a downstream target of NF-κB signaling, is overexpressed in ectopic lesions and the serum of endometriosis patients." (PMID 34266426, 2021). "As up-regulation of VCAM-1 in malignant cells is associated with recruitment of tumor-associated monocytes and macrophages and immune escape of the tumors, we postulate that LINC01133 dependent VCAM-1 regulation in endometriosis epithelial cells may be related to immune surveillance of the lesions." (PMID 34445100, 2021). "However, the exact role and mechanism of VCAM-1 in endometriosis remains unclear." (PMID 31443713, 2019). "The significance of this study was to clarify the role of VCAM-1 in TGF-β1-mediated proliferation and invasion of endometriotic cells, thereby providing new insights into the pathological mechanism of endometriosis." (PMID 31443713, 2019). "The results of bioinformatics analysis suggested that EPAS1, F8, VCAM1, and VWF might be highly expressed in endometriosis." (PMID 41188339, 2025). "Furthermore, the levels of cell adhesion molecules such as ICAM-1, VCAM-1, and CD44, which modulate cell–matrix and cell–cell attachments, are increased in the serum, peritoneal fluid, and endometrium of patients with endometriosis." (PMID 35409294, 2022). "Recently, we have shown that the levels of expression of VCAM-1 are increased in tissue samples of women with endometriosis, compared to women without the disease." (PMID 34445100, 2021). "For instance, we did not detect the expression of TGF-β1 and VCAM-1 in eutopic endometrium of patients with endometriosis." (PMID 31443713, 2019). "Moreover, in endometriosis, the expression changes of VCAM-1 and ICAM-1 play a crucial role, and the ratio of soluble VCAM-1 to soluble ICAM-1 may serve as a potential biomarker." (PMID 38660311, 2024). "Knockdown of VCAM-1 impedes TGF-β1-mediated proliferation, migration, and invasion of endometrial cells, thereby indicating that VCAM-1 may serve as a therapeutic target for endometriosis." (PMID 31443713, 2019).
vasculitis (20 papers, 2012 to 2025). "Abnormal or dysregulated VCAM-1 activation is linked to vasculitis and inflammatory disorders, both of which are key features of anthrax pathogenesis." (PMID 22347621, 2012). "Furthermore, the emergence of severe vasculitis due to HCV-associated MC was shown to be dependent on the induction of adhesion molecules including VCAM-1 and ICAM-1, both involved in mononuclear respectively polymorphonuclear and mononuclear cell recruitment during vasculitis." (PMID 25419735, 2014). "ICAM-1 and VCAM-1 are both important molecules in hyperglycemic brain injury produced by vascular instability, whether in terms of stimulating leukocyte adhesion, aggregation, or chemotaxis to cause vasculitis or the formation of cerebral atherosclerotic plaque." (PMID 40224490, 2025). "It is remarkable that AZU1 and VCAM1 hypomethylated in their genes presumably combine their partners (e.g., chemokines and adhesion receptors) to trigger vasculitis that can be observed in most of autoimmune conditions including RA and SLE." (PMID 30159339, 2018). "The disturbance of TLR signaling in pSS and the overactivation of type I IFN system in SLE owed to aberrant DNA methylation were confirmed, and AZU1 and VCAM1 were presumably involved in the pathogenesis of vasculitis." (PMID 30159339, 2018). "Elevated soluble vascular cell adhesion molecule-1 (VCAM-1) was likely to contribute to the involvement of vasculitis in HCV-related MC." (PMID 22988469, 2012). "These activated leukocytes and proinflammatory cytokines may enhance vasculitis and disrupt endothelial function and integrity, leading to the further release of VCAM-1." (PMID 33732102, 2021). "Indeed, the upregulation of ICAM-1 and VCAM-1, mediated by inflammatory cytokines and cellular stress, has been related to the leukocyte-induced ED, vascular thrombosis, and disruption of vascular walls observed in childhood vasculitis and KD." (PMID 39769085, 2024). "The role of oxidative stress in BPPV has been demonstrated with increased expression of VCAM-1 and d-ROM, which confirms angiitis’s existence and supports vascular involvement in BPPV." (PMID 36004953, 2022). "This study revealed the effects of LA on endothelial cell activation, NLRP3, IL-1β, TNF-α, IL-32, and CCL-2, VCAM-1, MCP-1, and the spleen tyrosine kinase (Syk)--p38/JNK signaling axis and its effect on vasculitis in rats." (PMID 30158835, 2018).